FKBP5 (FKBP prolyl isomerase 5)
Diseases named in the same sentence as FKBP5 in open-access papers (continued):
Sharing a sentence is not in itself a finding about the gene and the disease.
stress-related disorder (29 papers, 2014 to 2026). Stress-related disorders are mental health disorders that are a result of an atypical response to both short and long-term anxiety due to physical, mental, or emotional stress. "The FKBP5 gene, which encodes FK506-binding protein 5, is implicated in various trauma- and stress-related disorders, as well as alcohol use and withdrawal." (PMID 39484582, 2024). "A previous study showed that participants exposed to childhood abuse and carrying the TT genotype of the FKBP5 SNP rs1360780 had an increased susceptibility to stress-related disorders." (PMID 35787810, 2022). "FKBP5 was first associated with stress-related disorders in 2004 and has been studied extensively over the past 15 years with regard to stress regulation and sensitivity." (PMID 33649453, 2021). "SNPs in the FKBP5 gene, which cause the high expression of FKBP5, have been fundamentally linked to stress-related disorders, especially in psychiatric disorders." (PMID 34476212, 2021). "Steroid receptor encoding FKBP5 gene (FK506-binding protein 5) is reported to be involved in the pathogenesis of stress-related disorders by altering GR sensitivity." (PMID 32932645, 2020). "The gene encoding FK506 binding protein 51 (FKBP5), located on chromosome 6p21.31, is a highly interesting target for GxE as it is considered a shared etiological factor underlying stress-related disorders." (PMID 29466454, 2018). "For instance, there have been efforts to develop drugs that block FKBP5 activity in order to modify the risk for the development of stress-related disorders based on research conducted within a diathesis stress framework." (PMID 29466454, 2018). "The co-chaperone FKBP5 is a stress-responsive protein-regulating stress reactivity, and its genetic variants are associated with T2D related traits and other stress-related disorders." (PMID 29170369, 2017). "We genotyped the intronic FKBP5 T>C polymorphism at rs1360780, which has been identified in GWAS as risk allele for stress-related disorders." (PMID 28686619, 2017). "The FKBP5 gene serves as a crucial modulator of HPA axis reactivity and holds a key position in influencing the risk of stress-related disorders." (PMID 38609904, 2024). "The FK506-binding protein 5 (FKBP5) has been recently proposed as a drug target for treatment of stress-related disorders." (PMID 27709495, 2017). "Although FKBP5 has been implicated in stress-related disorders, it has not been directly linked to HFD-induced metabolic fatty liver disease." (PMID 41699049, 2026). "The FK506 binding protein 51 (FKBP5) is a negative regulator of the glucocorticoid receptor (GR), the main driver of HPA axis regulation, and FKBP5 polymorphisms have been repeatedly linked to stress-related disorders in humans." (PMID 33649453, 2021). "Previous studies have proposed that compound with the ability to interact with FKBP5 could be beneficial in the treatment of stress-related disorders." (PMID 33925151, 2021). "Since the landmark study on the genetic association of FKBP5 with PTSD18, several preclinical and clinical studies examined the genetic modulation as well as peripheral and central expression of FKBP5 in stress-related disorders including PTSD and major depression." (PMID 32098997, 2020). "Known for its fundamental regulatory role of the hypothalamic-pituitary-adrenal (HPA) axis and glucocorticoid receptor (GR) function in the presence of stress, FK506-binding protein 5 (FKBP5) is a key modulator of stress-related disorders including PTSD14,16,17." (PMID 32098997, 2020). "Furthermore, interactions between the FKBP5 gene and early-life traumatic experiences (e.g., childhood sexual trauma) may increase the likelihood of stress-related disorders later in the life." (PMID 37628589, 2023).
stress-related disorder (continued). "Future studies on traumatized/unexposed individuals both with and without stress-related disorder might help to further disentangle effects of CT on FKBP5 DNAM and associated HPA-axis dysfunctions from those related to psychiatric conditions." (PMID 32488091, 2020). "In recent studies of psychiatric phenomena, the functional impact of stress-related hypomethylation of genetic loci known to regulate stress responses (e.g., FK506 binding protein 5 (FKBP5)) suggest that this process may be relevant to many stress-related disorders." (PMID 26809779, 2016). "Being a stress-related disorder, HPA axis regulator genes have been extensively studied—such as the glucocorticoid receptor (GR) and FK506 binding protein 51 (FKBP5) genes." (PMID 33019527, 2020).
prostate carcinoma (27 papers, 2007 to 2025). A carcinoma that arises from epithelial cells of the prostate gland. "In tissue resection specimens from EAC patients, FKBP5 expression was positively associated with proliferation as measured by Ki-67 expression, which was also observed in the prostate cancer weight loss clinical trials." (PMID 34202278, 2021). "Mutation and deep deletion of FKBP5 are fairly infrequent in prostate cancer (≤1.22%), however FKBP5 down-regulation has been linked to CRPC and increased AKT signaling." (PMID 32630372, 2020). "Although FKBP5 knockout mice show normal androgen signalling, it has been linked to AR signalling and prostate cancer." (PMID 21119664, 2011). "Prior studies have shown that FKBP5 is highly expressed across multiple tissues and significantly contributes to drug resistance in various cancers, including breast and prostate cancers, multiple myeloma, acute lymphoblastic leukemia, and melanoma." (PMID 40771481, 2025). "Depletion of either FKBP5 or FKBP4 in prostate cancer cells reduces AR dimer formation, chromatin binding, and phosphorylation, suggesting defective AR signalling." (PMID 41249932, 2025). "Among them, the FKBP5 is reported to be overexpressed in the primary tumors of brain cancer, prostate cancer, lymphoma, head and neck cancer, colorectal cancer, and downregulated in pancreatic cancer." (PMID 38887841, 2024). "A number of genetic alterations in genes that encode AKT regulators have been linked to prostate cancer, including kinases (e.g., PDK1), binding proteins (e.g., FKBP5), and phosphatases (e.g., PHLPP1, PHLPP2, and PP2A)." (PMID 32630372, 2020). "DNAH8 was also positively associated with NKX3.1 (correlation coefficient 0.15, upper limit 0.23, lower limit 0.08, and p < 0.05) and FKBP5 (correlation coefficient 0.08, upper limit 0.15, lower limit 0.01, and p < 0.05) expression in prostate cancer." (PMID 27363033, 2016). "According to the Oncomine, FKBP5 is overexpressed in brain cancers, prostate cancer, lymphoma, head and neck cancer, and melanoma." (PMID 21119664, 2011). "Recent studies have identified a long-range activation of FKBP5 transcription in prostate cancer cells by the AR via distal intronic enhancers." (PMID 21119664, 2011). "Considering the link between HSPs and AR activity, we next investigated the impact of NXP800 on AR signaling, demonstrating a decrease in AR-FL and AR-V7 protein expression, and also in expression of AR-responsive genes (KLK2, KLK3, TMPRSS2, and FKBP5), across all three prostate cancer cell lines." (PMID 39787247, 2025). "The finding that androgen-induced expression of FKBP5 was inhibited by mirin in all three cell lines argues that MRE11 complex function is critical for transcription in prostate cancer cells, which is consistent with the siRNA results published by another group." (PMID 30305041, 2018). "Cells in which FKBP5 was overexpressed displayed a considerable stabilization of the AR protein, which is a versatile protein capable of reprogramming genomic activity in prostate cancer and probably also in other cancers." (PMID 25460502, 2014). "In contrast, another study focused on prostate cancer revealed a decrease in the mRNA levels of AR and AR-V7 (constitutively active variants), along with their targets kallikrein-related peptidase 3 (KLK3), FK506-binding protein 5 (FKBP5), and NKX3, following MLN4924 treatment and NAE knockdown." (PMID 39623094, 2024). "Therefore, FKBP5 might serve as a novel drug target to help disrupt AR-mediated signalling in prostate cancer." (PMID 21119664, 2011). "Additionally, blockade of AR pathways attenuates FKBP5 expression, which is androgen dependent in prostate cancer cells, resulting in increased AKT phosphorylation due to a reduction in PHLPP protein levels since FKBP5 is a molecular chaperone for the AKT phosphatase PHLPP." (PMID 22110995, 2011).
prostate carcinoma (continued). "The well‐known AR target genes TMPRSS2 and FKBP5 show enhanced chromatin accessibility, as assessed by ATAC signals, in prostate cancer samples (TCGA‐PRAD)." (PMID 38483933, 2024). "A recent study uncovered a mechanism in which FKBP5 is found to form a complex with HSP90 and promote AR signaling in prostate cancer." (PMID 32316460, 2020). "We treated prostate cancer cells with these inhibitors to determine their impacts on AR signaling by measuring AR targeted transcription of PSA, TMPRSS2 and FKBP5 genes." (PMID 26009876, 2015). "Transcript analysis of additional prototypical AR‐regulated genes FKBP5, KLK2, NKX3.1, and TMPRSS2 shows a similar pattern of expression to PSA and Ki67, indicating general inhibition of androgen signaling by bicalutamide in prostate cancer PDEs." (PMID 30117261, 2018). "In order to investigate if 11KT and 11KDHT demonstrate androgenic activity on endogenous AR-regulated genes, the mRNA expression levels of KLK3 (NM_001030047), FKBP5 (NM_001145775) and TMPRSS2 (NM_001135099) were assessed in two androgen dependent prostate cancer cell lines, LNCaP and VCaP." (PMID 27442248, 2016). "In prostate cancer, androgen-activated nuclear AR functions as a classical transcription factor with relatively well-characterized transcriptional repertoire, including genes such as PSA, KLK2, FKBP5, and TMPRSS2, the alteration of which promotes prostate tumor aggressiveness." (PMID 38326303, 2024). "The FKBP5 gene has been described as strongly androgen-regulated in several reports, and western blot analysis shows androgen to increase its protein levels in LNCaP cells; however, there are no reports discussing the impact of its down-regulation on prostate cancer models." (PMID 36611998, 2022). "Both DHT and enzalutamide had the anticipated impact on canonical AR genes (FKBP5 and NDRG1) in an androgen-sensitive prostate cancer cell line and in differentiated hBECs (Donor B1)." (PMID 35110354, 2022).
anxiety disorder (23 papers, 2011 to 2025). A category of psychiatric disorders which are characterized by anxious feelings or fear often accompanied by physical symptoms associated with anxiety. "Supporting this notion, a recent study in patients with anxiety disorders provided initial evidence that pre- to post-treatment changes in FKBP5 methylation were strongly associated with treatment outcome at six-month follow-up but not at post-treatment." (PMID 33825945, 2021). "Overall, this study constitutes a basic step toward understanding the underlying mechanisms of Fkbp5 signaling in the ovBNST and their role in stress-induced anxiety disorders." (PMID 34872938, 2021). "In this study we provide novel evidence that DNA methylation changes at FKBP5 intron 7 are associated with response to exposure‐based cognitive behavior therapy in adults with anxiety disorders." (PMID 30334356, 2019). "In addition, we previously reported allele‐specific changes in FKBP5 promoter methylation were associated with response to Cognitive Behavioural Therapy (CBT) in children with anxiety disorders." (PMID 30334356, 2019). "The impact of FKBP5 on the efficacy of CBT/iCBT for anxiety disorders has been rigorously investigated." (PMID 37497400, 2023). "FKBP5 DNA methylation has been also associated with response to psychotherapy in PTSD, children with anxiety disorders, and agoraphobia." (PMID 36171872, 2022). "FKBP5 SNPs and gene expression levels are associated with the onset of PTSD and anxiety disorder in humans." (PMID 27527158, 2016). "Previous studies imply that the abnormality of certain genes is associated with anxiety disorders, such as CRHR1, FKBP5, CREB, Egr-1, Glo1, Gsr, AC8, CaMKIV, dystrophin, HTTLPR and COMT Met158." (PMID 22681774, 2012). "The current research indicates that FKBP5 may affect CBT/iCBT efficacy in patients with anxiety disorders, though the specific genetic mechanism remains to be elucidated." (PMID 37497400, 2023). "This is in agreement with previous findings, suggesting that peripheral FKBP5 RNA expression is induced by elevated glucocorticoid levels in patients with affective and anxiety disorders, which could also be confirmed in a human lymphoblastoid cell line model." (PMID 30678080, 2019). "Furthermore, commonly used antidepressants seem to indirectly modulate the HPA axis, suggesting that medications that directly affect the axis, such as CRF agonists of FKBP5 inhibitors, could be a promising treatment intervention for anxiety disorders." (PMID 40508224, 2025). "FKBP5 alleles may also influence exposure-based psychotherapy in PTSD, and FKBP5 allele-specific alterations in methylation have been associated with differential responses to psychological treatments for anxiety disorders." (PMID 30610352, 2019). "With our association study in a cohort of pregnant women without further risk factors for depressive or anxiety disorders, we could not show that candidate single nucleotide polymorphisms within the genes FKBP5, NR3C1, and CRHR1 are associated with EPDS values during or after pregnancy." (PMID 24741566, 2014). "Consistent with our study, baseline FKBP5 methylation was not related to eventual responder status to either cognitive behavior therapy (CBT) in children with anxiety disorders or exposure therapy (n = 8 responders or 8 non-responders) in veterans with PTSD." (PMID 30279666, 2018).
Insulin resistance (23 papers, 2015 to 2025). Increased resistance towards insulin, that is, diminished effectiveness of insulin in reducing blood glucose levels. "Elevated FKBP5 expression is associated with insulin resistance, impaired glucose metabolism, and increased inflammation levels, all of which are characteristic features of T2D." (PMID 40017583, 2025). "Polymorphisms in FKBP5 are also associated with insulin resistance and obesity, further connecting this gene to metabolic diseases." (PMID 40017583, 2025). "FKBP5 expression and blood glucose/insulin resistance are positively correlated in humans, and a mutation causing elevated FKBP5 is associated with reduced weight loss following bariatric surgery." (PMID 34692682, 2021). "Fkbp5 is highly upregulated by glucocorticoid stress-response hormones in adipose tissue and is implicated as a critical gene in glucocorticoid-induced insulin resistance." (PMID 34972124, 2021). "FKBP5 SNPs have also been linked to insulin resistance and T2D traits and reduced weight loss following bariatric surgery." (PMID 32958048, 2020). "While this study was limited by a small sample size, it agrees with our findings on the association between higher intronic FKBP5 methylation and an increased risk for obesity and insulin resistance." (PMID 32958048, 2020). "In conclusion, we have found that FKBP5 expression in human subcutaneous adipose tissue is associated with T2D traits and markers of insulin resistance." (PMID 30032404, 2018). "Accordingly, FKBP5 SNPs have been associated with type 2 diabetes, insulin resistance, and elevated serum triglycerides." (PMID 29206196, 2017). "Reports have suggested that SNPs within the FKBP5 gene may be linked to the susceptibility to develop insulin resistance and dyslipidemia." (PMID 35787810, 2022). "FKBP5 expression is associated with insulin resistance, and its activity is regulated by FOXO1." (PMID 35642195, 2022). "FKBP5 is confirmed to be most expressed in human skeletal muscle and adipose tissue in all study tissues, and increased FKBP5 expression in omental adipose tissue is associated with insulin resistance." (PMID 34237933, 2022). "Moreover, it is notable that previous studies have shown that FKBP5 is highly expressed in muscle and adipose tissue, and human FKBP5 is associated with type 2 diabetes(T2D) and with markers for both insulin resistance and obesity." (PMID 35787810, 2022). "FKBP5 gene expression levels were also found to be associated with markers of insulin resistance." (PMID 30032404, 2018). "Studies have shown that GC exposure can lead to changes in FKBP5 methylation, further disrupting glucose metabolism and exacerbating insulin resistance." (PMID 40017583, 2025). "FKBP5 influences the body's responses to stress and inflammation, which are known to exacerbate insulin resistance." (PMID 40017583, 2025). "Hypomethylation of cg22363520 enhances FKBP5 expression, amplifies stress responses, disrupts glucose metabolism, and promotes insulin resistance." (PMID 40017583, 2025). "In humans, FKBP5 expression in abdominal scWAT correlates positively with markers of insulin resistance and type 2 diabetes." (PMID 38671495, 2024). "In animal studies, deletion or inhibition of FKBP5 causes decreased WAT mass and protection against diet-induced weight gain, insulin resistance, and hepatic steatosis." (PMID 38671495, 2024). "FKBP5 DNA methylation correlated with adiposity, insulin resistance, and systemic inflammation; it inversely correlated with the gene’s mRNA levels and was positively associated with adiposity, metabolic, and inflammatory parameters." (PMID 38786025, 2024). "FKBP5 is related to decreased glucose uptake in omental tissue, insulin resistance, decreased levels of high-density lipoproteins (HDL), and stimulation of the inflammatory response." (PMID 37512517, 2023).